CCR4 (C-C motif chemokine receptor 4)
Diseases named in the same sentence as CCR4 in open-access papers (continued):
Sharing a sentence is not in itself a finding about the gene and the disease.
autoimmune disease (11 papers, 2009 to 2025). A disorder resulting from loss of function or tissue destruction of an organ or multiple organs, arising from humoral or cellular immune responses of the individual to their own tissue constituents. "Th17 and Th22 proinflammatory cells, implicated in the pathogenesis of many autoimmune diseases, cancer and more, are a very minor part of the CCR4+ CD4 cells and are CD45R0." (PMID 34680079, 2021). "Transient CCR4+ effector Treg depletion will be advantages to avoid the risk of autoimmune diseases." (PMID 29873181, 2018). "As with other autoimmune diseases, AS patients exhibit an imbalance of CCR4+CCR6+ helper T cells and regulatory T cells." (PMID 23637848, 2013). "However, ipilimumab or anti-CCR4 Abs can induce autoimmune disease in cancer patients, and management to treat the adverse effects is therefore required." (PMID 34882757, 2021). "The great complexity of CCR4 regulation and activities in the context of CNS autoimmune diseases may explain, at least in part, discrepant findings between studies utilizing mutant mice and pharmacological approaches." (PMID 29099057, 2017). "In the study of autoimmune diseases, it has been found that CMTM1 may be involved in the occurrence and development of arthritis by interacting with the C–C chemokine receptor 4 (CCR4)." (PMID 33585698, 2021). "However, mogamulizumab also reduced the number of CCR4+ regulatory CD4 T cells, which was occasionally observed as a severe autoimmune disease." (PMID 29212930, 2018). "However, our study demonstrated that after IFN-â treatment, the percentage of CD4+CCR4+ significantly increased in the NMO group, suggesting up-modulation of the Th2 response by IFN-â in autoimmune diseases involving the humoral immune system." (PMID 23202893, 2012).
colitis (10 papers, 2014 to 2024). Inflammation of the colon. "Different from the closely related molecule CCR4, which has been previously shown to drive pathogenic inflammatory reactions in mouse colitis models, Ccr8−/− mice developed highly increased mucosal damage compared to control mice." (PMID 33613532, 2020). "Taken together, these data support the idea that over-expression of CD200 in CD200tg mice enhances CCR4 dependent Foxp3+ Treg cell migration to the colon in mice to suppress a chronic inflammatory response associated with chronic DSS colitis." (PMID 26841120, 2016). "Evidence also shows that C‐C motif ligand 17 (CCL17), the chemokine ligand of CCR4 is required to induce colitis in mice." (PMID 39678631, 2024). "On the other hand, colitis rats receiving feed with high-molar-mass oat beta-glucan (CβGh+) resulted in higher expression of only four genes (Ccl19, Ccr4, Ccr8, Cxcl9)." (PMID 35163326, 2022). "Several genes such as Gata3, Itk, Ccl8, Ccl22, Ccr4, Crlf2, Il9r, Il1rl1, and Arg2 are regulated concordantly in T-cell transfer colitis, acute DSS colitis and the time point representing high inflammation in the DSS time course." (PMID 34136502, 2021). "The homing functions were owing to the fact that MSCs expressed many chemotaxis receptors such as CCR1, CCR2, CCR4, CCR5, CCR9, CXCR1, and CXCR5; the CCR2 and CCR4 were major migration helpers of MSCs in colitis, and CXCR4 combined with SDF-1 can promote MSCs migration." (PMID 30687760, 2018). "CCL17 is increased in the inflamed mucosa of murine colitis, and CCL17-deficient animals are protected from colitis induced by DSS,103 although the ability of mice lacking CCR4+ T-cells to develop florid colitis suggests contribution by CCR4+ innate effector cell types." (PMID 30137309, 2018). "The crucial role of chemokine-receptor-dependent migration in functional regulation is demonstrated in several experiments including a mouse model of colitis and IBD, where CCR4-deficient Treg had impaired migration to the mesenteric lymph nodes and therefore failed to prevent colitis." (PMID 24639678, 2014). "In a rat adoptive transfer model of inflammatory bowel illness, Ccr4/Treg cells failed to aggregate in the mesenteric lymph nodes to suppress colitis." (PMID 37259456, 2023). "Although the transfer of CCR4+ regulatory T cells isolated from spleens and lymph nodes protects against the development of colitis, the transfer of CCR4− regulatory T cells fails to prevent the development of disease." (PMID 30584243, 2018).
eosinophilia (10 papers, 2011 to 2024). "Our study demonstrated that CCR4 blockaded by compound 8a effectively attenuated airway hyperresponsiveness, airway eosinophilia and Th2 cytokines." (PMID 29118379, 2017). "CCR4 blockaded by compound 8a effectively inhibits Th2 cytokines and consequent airway eosinophilia and hyperresponsiveness." (PMID 29118379, 2017). "However, in CCR8 deficient mice, Th2 cytokines and eosinophilia are not affected, suggesting the superiority of CCR4 in Th2 recruitment." (PMID 32024540, 2020). "Like the CCR4 antibody, the special Ab against TARC and MDC can also reduce airway eosinophilia and hyperresponsiveness in asthmatic mice elicited by OVA." (PMID 22907157, 2012). "In addition, CCR4 blockade decreases AHR, eosinophilia, Th2 cytokines and their recruitment representing an effective target for asthma treatment." (PMID 32024540, 2020). "Consistent with the higher percentage of CCR4+CD45RA−CD45RO+CCR7+ CD4+ T cells in patients without blood eosinophilia, atopic asthma patients without blood eosinophilia showed an increase of CRTH2+CD45RA−CD45RO+CCR7+ CD4+ T cells, compared to control subjects." (PMID 29507584, 2018). "Patients without blood eosinophilia showed a significantly higher percentage of CCR4+ CD4+ T cells (left)." (PMID 29507584, 2018). "Furthermore, mice lacking CCR4 have shown a reduction in peribronchial and airway eosinophilia when stimulated with A. fumigatus conidia in models of allergic aspergillosis." (PMID 39194909, 2024).
Sepsis (10 papers, 2010 to 2025). Sepsis is defined as life-threatening organ dysfunction caused by a dysregulated host response to infection. "Ccr4-/- mice exhibit decreased mortality in sepsis models associated with attenuated inflammation and reduced recruitment of macrophages to the peritoneal cavity." (PMID 37207205, 2023). "Our goal was to understand the roles of CCR4 and Tregs in the early event during severe sepsis and in the susceptibility of septic mice to a secondary infection with this fungus." (PMID 26197455, 2015). "Interestingly, CCR4 deficiency results in attenuated severity of murine polymicrobial sepsis and lipopolysaccharide-induced endotoxic shock, implicating this receptor in the pathogenesis of acute conditions." (PMID 21206747, 2010). "In a lipopolysaccharide model of sepsis, transgenic CCR4-/- knockout mice showed improved survival rates due to a significant reduction in pro-inflammatory cytokine release and associated sepsis." (PMID 32973504, 2020). "Our findings also demonstrate that CD43 drives a TH1 phenotype, as CD43-/- demonstrate significantly decreased IL-2+ CXCR3+ CD4+ (TH1-like) cells with a concomitant increase in IL-4+ CCR4+ CD4+ (TH2-like) cells in sepsis." (PMID 30226896, 2018). "This fact supports our work in using CCR4-/- mice to not only investigate the effects of this receptor but also the effects of Tregs during severe sepsis." (PMID 26197455, 2015). "Our work on Tregs and CCR4 contributes to the understanding of the long-term consequences of severe sepsis." (PMID 26197455, 2015). "Neutrophil recruitment and CFUs were also assessed in the WT and CCR4-/- animals in the NL groups to determine the expected migration during peritonitis and bacterial counts as two sepsis severity parameters for comparisons." (PMID 26197455, 2015). "Furthermore, CCR4 plays a beneficial role in recruiting immune cells to the site of infection, triggering a downstream immune response; however, CCR4 can also play deleterious roles, negatively impacting wound healing and contributing to sepsis." (PMID 32973504, 2020). "Furthermore, CCL22 signaling through CCR4 has been shown to promote the formation of cell–cell contacts and interaction with regulatory T cells, as well as regulatory T cell–mediated suppressive activity during severe sepsis." (PMID 40682363, 2025). "In addition, we suggest that CCR4 on Tregs modulates their suppressive effects and may act as a link between the innate response and long-term consequences of severe sepsis." (PMID 26197455, 2015). "Thus, at least in viral (present study) and polymicrobial sepsis, blockade of CCR4 may be beneficial from the therapeutic point of view, a tenet that must be tested further in patients." (PMID 21206747, 2010). "In a mice sepsis model, it was suggested that CCL17 through its receptor CCR4+ on Tregs has prolonged immunosuppressive effects." (PMID 40076848, 2025). "In this study, we investigated the role of CCR4, the CCL17/CCL22 chemokine receptor, in the innate and acquired immune responses during severe sepsis and the role of Tregs in effecting the outcome." (PMID 26197455, 2015). "In our first set of experiments, we demonstrated that CCR4, the receptor for CCL17 and CCL22, contributes to the establishment of an inadequate innate immune response during severe sepsis." (PMID 26197455, 2015). "Tregs bearing CCR4 have an exceedingly detrimental role in the CLP model, although it has not been described in the context of immunosuppression following sepsis until now." (PMID 26197455, 2015). "Such neutrophil accumulation was similar to that observed in WT and CCR4-/- mice subjected to non-lethal sepsis (NL-CCR4-/-), in which no migration failure was observed." (PMID 26197455, 2015).
Sepsis (continued). "Furthermore, CD43-/-septic mice exhibited a prominent Th2 skewing following sepsis relative to WT septic mice, as evidenced by a significant decrease in the frequency of IL-2+ CXCR3+ TH1 cells as a significant increase in the frequency of IL-4+ CCR4+ TH2 cells." (PMID 30226896, 2018).
Sézary syndrome (10 papers, 2018 to 2025). "Notably, a fully humanized anti-CCR4 monoclonal antibody, mogamulizumab, is currently used for the treatment of relapsed/refractory MF and Sézary syndrome (SS)." (PMID 37669110, 2023).
Autoimmunity (9 papers, 2017 to 2024). The occurrence of an immune reaction against the organism's own cells or tissues. "Both receptors are required for protection from autoimmunity, with results suggesting that CCR4 and CCR7 promote tolerance against different tissues." (PMID 37266571, 2023). "To evaluate this possibility, we assessed the presence of spontaneous autoimmunity/autoinflammation in multiple organs of WT, Ccr4−/−, Ccr7−/−, and DKO mice." (PMID 37266571, 2023). "We have shown before, that CCR4+ DCs capable to invade the brain during neuroinflammation in a model of CNS autoimmunity are specialized to produce GM-CSF." (PMID 33921690, 2021). "Further, Th17 cells expressing CXCR3+CCR6+ are associated with protection against Mtb, while those displaying CCR6+ CCR4+ are involved in autoimmunity." (PMID 28985739, 2017). "In addition, Sugiyama and colleagues demonstrated that the residual CCR4− eTreg cells and naive Tregs are sufficient to prevent deleterious autoimmunity when using anti-CCR4 mAb to decrease eTreg cells in the immune system." (PMID 34806028, 2021). "We also demonstrated that CCR4 and CCL17 are functionally involved in CNS autoimmunity by regulating DC functions." (PMID 33921690, 2021). "Regarding CCR4, increased expression in AN on CD4+ T cells, which may represent Th17 cells, could promote autoimmunity and chronic inflammation." (PMID 36226111, 2022). "Human (Hs) Roquin1 and Roquin2 are RNA-binding proteins that promote mRNA target degradation through the recruitment of the CCR4-NOT deadenylase complex and are implicated in the prevention of autoimmunity." (PMID 28165457, 2017). "Human Roquins are known to promote RNA degradation by recruiting the CCR4-NOT deadenylase complex, thus preventing autoimmunity." (PMID 38892048, 2024).
pulmonary fibrosis (9 papers, 2009 to 2024). Chronic progressive interstitial lung disorder characterized by the replacement of the lung tissue by connective tissue, leading to progressive dyspnea, respiratory failure, or right heart failure. "In mice, Ccl22 is produced during the pathogenesis of bleomycin-induced pulmonary fibrosis and Ccr4-/- mice are protected from pulmonary fibrosis." (PMID 39768150, 2024). "Bleomycin-induced pulmonary fibrosis increases Ackr2 expression, while CCR4-/- mice, protected from fibrosis, exhibit higher Ackr2 levels." (PMID 39768150, 2024). "Previous reports suggested that CCL17 and the ligand CCR4 contribute to development of pulmonary fibrosis by inducing infiltration of alveolar macrophages and Th2 cells in a bleomycin mouse model." (PMID 31369605, 2019). "Moreover, the knockdown of CCR4 by CCR4-siRNA or blockade by CCR4 antagonist C-021 was able to ameliorate pulmonary fibrosis pathology in mice." (PMID 37681924, 2023). "The study showed that CCL17 is a pro-fibrotic mediator of lung fibroblasts, suggesting that CCL17 or CCR4 inhibition may serve as an effective strategy to suppress lung fibroblast activation and attenuate pulmonary fibrosis progression." (PMID 37681924, 2023). "Interestingly, in a commonly used model of bleomycin-induced lung fibrosis, CCR4−/− mice showed a decreased inflammatory and fibrotic response compared to WT mice." (PMID 30245686, 2018). "For instance, CCL22 and CCL17, secretd by M2 macrophages, can recruit CCR4+CD4+ T helper 2 cells, thereby contributing to the pathophysiology of pulmonary fibrosis." (PMID 38789926, 2024). "Humans and mice with pulmonary fibrosis were reported to have significantly elevated CCL17 and CCR4 expression in lung tissues, and the severity of pulmonary fibrosis decreased after neutralization of CCL17." (PMID 34943853, 2021). "We examined the expression of CCR4, a specific receptor for CCL22 and CCL17, in bronchoalveolar lavage (BAL) fluid cells, as well as the levels of CCL22 and CCL17, to elucidate their pathophysiological roles in pulmonary fibrosis." (PMID 19715610, 2009).
Arthritis (8 papers, 2006 to 2026). Inflammation of a joint. "Compound 22, a CCR4 inhibitor, ameliorated arthritis by reducing Th17 cell migration into the joints of CIA mice." (PMID 36860872, 2023). "CCR4, CCR6, CCR7, CCR9, CXCR5, and CXCR6 deficiency ameliorated arthritis in CIA mice by suppressing the migration of Th17 cells (CCR4), DC (CCR7), and CD11b+ splenocytes (CCR9)." (PMID 36860872, 2023). "Evidence of CCL17 contributing to pain responses via CCR4 predominantly comes from murine models of arthritis, demonstrating that CCL17 can drive arthritic pain and may contribute significantly to the development of chronic pain." (PMID 41291326, 2025). "B cells from the SF of arthritis patients showed a significant increase in the surface expression of CCR1, CCR2, CCR4, CCR5 and CXCR4 with respect to PB." (PMID 29880013, 2018). "Analogous to the present observations, synovial fluid from patients with arthritis contained comparable numbers of CD4+ memory T cells expressing CLA, integrin α4β7 and CCR4 as peripheral blood." (PMID 16824229, 2006). "Additionally, other studies have shown that the expression of CCR1, CCR2, CCR4, CCR5, and CXCR4 on the surface of B cells in synovial fluid (SF) of arthritis patients is significantly increased." (PMID 41481752, 2026). "OCPs from patients with arthritis had higher expression of CCR1, CCR2, CCR4, CXCR3, and CXCR4." (PMID 28619088, 2017).
liver cancer (8 papers, 2014 to 2025). An epithelial or non-epithelial malignant neoplasm that arises from the liver. "A study of HBV-associated liver cancer showed that CCR4+ Treg were predominantly infiltrated in HBV+ tumor tissue, which expressed IL-10 and IL-35 more than CCR4− Treg and was more potent at suppressing CD8+ T-cells, which led to resistance to sorafenib." (PMID 41226585, 2025). "Moreover, interfering with a CCR4 antagonist or a N-terminus recombinant protein of CCR4 (N-CCR4-Fc) exerts a prominent effect on conquering sorafenib resistance and sensitizes liver cancer to PD-1 checkpoint inhibitor." (PMID 36071839, 2022). "In our CCR2/CCR4 double-K/O model, Foxp3+ Treg infiltration was reduced, while a meaningful infiltration of CD8+ T cells was observed in our CCR2/CCR4 double-K/O model, similar to what was obtained in a model of liver cancer following CCR2 K/O or neutralization." (PMID 35980743, 2022). "Not only CCR4 but also its ligands CCL17 and CCL22 were found to be highly overexpressed in human and mouse liver cancers." (PMID 37081509, 2023). "Interestingly, a recent study has also reported that in liver cancer cells IMP1 could be associated with the CCR4-NOT RNA decay machinery in enhancing the degradation of its associated lncRNA HULC." (PMID 29669595, 2018). "In addition to CCR4, its ligands CCL17 and CCL22 found to be elevated in liver cancer, which facilitate Tregs cell infiltration to the tumors leading to the suppression of anti-cancer immunity by TGF-β1 production, and further establishment of a favorable microenvironment for tumor growth." (PMID 37081509, 2023).
dermatitis (7 papers, 2020 to 2025). An inflammatory process affecting the skin. "The expression of CLA and CCR4 has been associated with the pathogenesis of several skin disorders including autoimmune and oncological diseases." (PMID 40277930, 2025). "The loss of CCR4 on murine Tregs impairs Treg accumulation in skin and lung tissues, with complete loss of CCR4 in the Treg cell compartment leading to severe dermatitis, pneumonitis and lymphadenopathy." (PMID 38283365, 2023). "In vivo, homing assay, functional blockade of CCL27 by anti-CCL27 monoclonal antibody prevented CCR4-deficient T cells from migrating to the site of skin inflammation but not in wild-type mice." (PMID 40040698, 2025). "The CCR4 specific ligands, CCL17 and CCL22, induce persistent immune cell accumulation at skin inflammation sites." (PMID 34451592, 2021). "Therefore, CCL17 and CCR4 are important in lymphocyte-selective skin homing, and both are synergistically involved in the interaction between TEM homing to the skin and the site of skin inflammation and vascular endothelium." (PMID 40040698, 2025).
head and neck squamous cell carcinoma (7 papers, 2021 to 2025). A squamous cell carcinoma that arises from any of the following anatomic sites: lip and oral cavity, nasal cavity, paranasal sinuses, pharynx, larynx, and salivary glands. "Blocking the CCL2/CCR4 axis in Tregs evokes an anti-tumor immune response in a model of head and neck squamous cell carcinoma while blocking of CCL2/CCR4 axis on CTLs could be detrimental as argued in the study." (PMID 34804061, 2021). "In addition, previous study also indicated that CCR4 could be a prognostic biomarker and correlated with immune infiltrates in head and neck squamous cell carcinoma." (PMID 35619698, 2022). "CCR4+ head and neck squamous cell carcinoma (HNSCC), compared to CCR4-, promotes lymph node metastasis with TAM-derived CCL22." (PMID 39199574, 2024). "In addition, pharmacological inhibition of CCL2/CCR4/Vav2/Rac1/MLC signaling pathway can effectively reduce the motility of cancer cells, thereby inhibiting local invasion and distant lymph node metastasis in head and neck squamous cell carcinoma (HNSCC) cells." (PMID 41341593, 2025).